OLIG2 (oligodendrocyte transcription factor 2)
Diseases named in the same sentence as OLIG2 in open-access papers (continued):
Sharing a sentence is not in itself a finding about the gene and the disease.
tumor (283 papers, 2005 to 2026). "Immunohistochemical staining confirmed a complete loss of OLIG1 and OLIG2 protein expression in tdT+ tumor cells of Olig1/2F/+; ISF/+ mice, validating the efficacy of the conditional knockout system in this study." (PMID 40428395, 2025). "Depletion of mitotic Olig2+ progenitors or Olig2 ablation impeded tumor initiation, indicating that glial lineage-associated OLIG2+ progenitors are cellular origin of SHH MBs and OLIG2-driven oncogenic networks as potential therapeutic targets." (PMID 38355808, 2024). "OLIG2 encodes a core neurodevelopmental transcription factor that controls a stem-like tumor-propagating cell state in GBM47." (PMID 38971800, 2024). "The presented study revealed that OLIG2 was high expressed in 57.5% (42/73) cGBM patients, consistent with previous research, which seems associated with tumor malignancy." (PMID 37001387, 2023). "Tumor location, diffuse versus circumscribed tumoral architecture, Olig2 expression, type of histone gene mutations and DNA-methylation profiling must be considered in the integrated diagnosis." (PMID 36104744, 2022). "Stem cell marker Olig2, which is also associated with the classical subtype in this study, is integrated in regulating stem cell proliferation and driving tumor growth." (PMID 33066251, 2020). "Positive reaction with OLIG2 (6 tumours) was always associated with the presence of PAX3/7-FOXO1 rearrangement." (PMID 31493794, 2019). "Notably, loss of either ASCL1 or OLIG2 had only modest effects on tumor progression and survival, likely due to redundant functions of these two transcription factors given their extensive shared binding in GBMs." (PMID 39609428, 2024). "In addition, H&E stains of tumor sections showed that orthotopic grafts expressing 3KR Olig2 had much more severe cell loss as compared with those expressing WT Olig2." (PMID 32483381, 2020). "Moreover, Olig2 has been recently identified as a key component of the transcriptional regulatory network activated upon combination of tumour suppressor and oncogene mutations in astrocytes." (PMID 29759978, 2018). "Moreover, NCT-503 treatment led to a decrease in the number of tumor cells expressing the stem cell markers SOX2 and Olig2, an increase in the expression of markers associated with DNA repair, and an increase in tumor cell apoptosis." (PMID 40102981, 2025). "Furthermore, despite utilizing different approaches and driver mutations to induce tumor formation, the loss of NFIA or OLIG2 was also accompanied by significant decreases in tumor cell proliferation resulting in an increase in survival for their respective mouse models." (PMID 32573857, 2020). "Our results obviously need further confirmation on the larger series of RMS tumours, nevertheless already obtained results indicate that positive OLIG2 alone or in association with other markers may serve as a substitute for the presence of PAX3/7-FOXO1 gene fusion." (PMID 31493794, 2019). "Mechanistically, OLIG2 recruited HDAC7 to repress CXCL10 transcription, inducing STAT3 activation in tumor-associated macrophages (TAMs) and decreasing CD8+ T cell infiltration and activation." (PMID 41591814, 2026). "In IHC staining with antibodies to the oligodendrocyte marker protein Olig2 and the mature astrocyte marker GFAP, as well as the stem cell marker Sox2, a large number of Olig2+ and Sox2+ cells were observed in the tumor node relative to the peritumoral zone." (PMID 41009560, 2025). "Immunohistochemical analysis of tumor tissues in the subventricular zone (SVZ) demonstrated widespread co-expression of OLIG1 and OLIG2 in tdT+ tumor cells." (PMID 40428395, 2025).
tumor (continued). "Olig2 expression was observed in the nuclei of tumor cells, with intense positive staining particularly prominent in perinecrotic regions." (PMID 40282990, 2025). "The percentages of SOX2‐, OLIG2‐, and Ki67‐positive cells in the six tumor specimens demonstrated that this heterogeneity was highly similar to that of the corresponding parental tumors." (PMID 40112194, 2025). "This regulation represses genes like SOX3, which oppose the mitotic and OLIG2-positive tumor phenotype." (PMID 40565099, 2025). "First, we systematically evaluated the expression profiles of OLIG1 and OLIG2 across major tumor types using the TCGA database." (PMID 40428395, 2025). "Antibodies to OLIG2, a marker of oligodendrocytes and oligodendrocyte progenitor cells, also co-label IL-33 positive cells in the tumor microenvironment." (PMID 39931535, 2025). "In the context of GBM, Olig2 contributes to the maintenance of tumor-initiating cells and regulates pathways that promote cell survival and proliferation." (PMID 40282990, 2025). "PHGDH ablation decreased SOX2 and Olig2 positive tumor cells in GBM xenografts, indicating a reduced GSC reservoir." (PMID 40102981, 2025). "Analysis of coronal sections across the tumor-bearing brain showed that a majority of IL-33-positive cells (≥80%) also co-express OLIG2, and more than half (around 60%) co-express CNPase while co-labeling with GFAP is seen in 5% of the IL-33-positive cells." (PMID 39931535, 2025). "We observed two different invasion modes of OLIG2+ tumor cells, namely the diffuse spread of individual cells into the surrounding physiological brain parenchyma and vessel co-option of single cells." (PMID 41339360, 2025). "Histological examination confirmed an infiltrative glial lesion: immunoreaction positive for GFAP and for oligodentrocyte transcription factor (OLIG2) in tumor cells." (PMID 40277798, 2025). "In contrast, Ascl1-OE significantly increased the percentage of OLIG2+ tumor cells in both P30 (89%) and terminal (87%) tumors compared to controls (dark green bars)." (PMID 39609428, 2024). "Subsequently, the binding of ASCL1 and OLIG2 to each other’s loci and to downstream target genes then determines the cell types and degree of migration of tumor cells." (PMID 39609428, 2024). "Transcription factors (TFs) like ASCL1 and OLIG2, which are co-expressed in GBMs (Module 8), play crucial roles in maintaining tumour cell heterogeneity and hierarchy." (PMID 39457550, 2024). "Tumor cells were positive for Olig2 and GFAP, while immunohistochemical staining for neuronal markers was negative." (PMID 38902810, 2024). "These functions are consistent with the proposed roles for ASCL1 and OLIG2 as core regulators of tumor-propagating cells." (PMID 39609428, 2024). "This highlights a discrepancy in SOX10+ versus OLIG2+ tumor cells, especially considering that Sox10 is transcriptionally regulated by OLIG2 within OPCs40." (PMID 39609428, 2024). "Analysis of cellular immunofluorescent intensity of GFP+ tumor cells confirmed that the level of ASCL1 was elevated by about 2-fold compared to control or Olig2-CKO tumor cells." (PMID 39609428, 2024). "In contrast, tumor cells with higher levels of OLIG2 relative to ASCL1, such as Ascl1-CKO tumors, favor activation of an OPC/oligodendrocyte program and a less diffuse tumor phenotype." (PMID 39609428, 2024). "When cell migration is terminated and tumor cells start to detach from the perivascular niche, OLIG2 is downregulated, and cells shift towards a MES-like state." (PMID 38473812, 2024). "As predicted, double CKO (dCKO) of both Ascl1 and Olig2 prevented tumor formation in approximately 80% of TNP-deleted mice (N = 16/20, 4 litters), while 20% developed slow-growing tumors that were not lethal until 4-6 months of age." (PMID 39609428, 2024). "Within control tumors, we found that 74% of tdTOM+ tumor cells were OLIG2+ at P30 but were decreased to 61% at terminal stages." (PMID 39609428, 2024).
tumor (continued). "Tumor cells showed regional immunohistochemical positivity for glial markers as Olig2 and GFAP, MIB-1 (Ki-67) proliferation index exceeded 25%." (PMID 38902810, 2024). "The tumor cells were positive for glial markers (GFAP, OLIG2) and markers of neuronal differentiation (synaptophysin, chromogranin) were focally expressed within the tumor." (PMID 38650040, 2024). "Conversely, the immunofluorescent levels of OLIG2 were lowered in Ascl1-OE tumor cells compared to Ascl1-CKO tumor cells." (PMID 39609428, 2024). "By P60 to terminal stages, GFP+ tumor cells infiltrated the striatum and cortex of both ipsilateral and contralateral hemispheres, similar to Olig2-CKO tumors." (PMID 39609428, 2024). "TAM depletion results in reduced tumor proliferation (%Ki67+ cells), Blbp+ and Olig2+ cell content (%Olig2+ and %Blbp+ cells) and Ccl5 expression." (PMID 38308315, 2024). "Medium expression of GFAP and limited expression of S100 and OLIG2 were detected in the NHA/HRasV12/TRIM24 S767/768A‐derived tumor xenografts." (PMID 38828688, 2024). "Although tumor cell subpopulations were similar between these two models, stem cell-derived MBs progressed faster, contained more Olig2-expressing stem-like cells and showed radiation-resistance." (PMID 38355808, 2024). "In this study we analyzed OLIG2 expression in MB subgroups and evaluated the effect of OLIG2 inhibition on tumor growth, either as a single intervention and in combinatorial therapies." (PMID 37333134, 2023). "As for tumor #21 and #22, the cells of the PDOs maintained the typical piloid morphology as well as the expression of OLIG2 (Fig EV4C)." (PMID 38037472, 2023). "The log-rank test indicated that gross total tumor resection and adjuvant therapy as well as high OLIG2 expression would contribute to the OS of cGBM patients in our present study." (PMID 37001387, 2023). "As SHH MB in patients show more heterogeneous OLIG2 expression, we studied MB tumor explant organoids (MBOs), which recapitulate key-aspects of tumor heterogeneity in vitro." (PMID 37333134, 2023). "As CT-179 specifically targets the OLIG2+ subset of tumor cells in MB, we used scRNA-seq to identify changes in cellular heterogeneity during CT-179 treatment." (PMID 37333134, 2023). "We therefore investigated the efficacy of anti-OLIG2 therapy in both single agent format, to define potential anti-tumor effects, and in multi-modal combinations as are typically needed in clinical treatment of MB patients." (PMID 37333134, 2023). "We investigated the anti-tumor potential of the small-molecule OLIG2 inhibitor CT-179, using SHH-MB patient-derived organoids, patient-derived xenograft (PDX) tumors and mice genetically-engineered to develop SHH-MB." (PMID 37333134, 2023). "Through this mode of action, CELF2 can repress genes such as SOX3, which we have shown to oppose the phenotype of mitotic/OLIG2-positive tumor cells." (PMID 37894405, 2023). "In this study, we demonstrate that the OLIG2 inhibitor CT-179 can target OLIG2-expressing tumor stem cells that are resistant to conventional therapies, and thus increase the efficacy of multi-modal therapy, most prominently in SHH-driven MB." (PMID 37333134, 2023). "Treatment with CT-179 in tumor-bearing mice resulted in a reduction of Olig2+ cells and markedly improved survival outcome." (PMID 37274223, 2023). "Cox regression analysis showed gross total tumor resection, high OLIG2 expression level and adjuvant therapy were independent favorable factors for the OS of cGBM patients." (PMID 37001387, 2023). "Tumor cells were diffusely positive for Synaptophysin, CD56, INI1 and SMARCA4 associated with negativity for GFAP, OLIG-2, EMA, BCOR, LIN28A and MIC-2." (PMID 36934287, 2023). "The tumor showed extensive microcalcifications and cells with oval, nuclei and a clear perinuclear halo (A), positive immunostaining for OLIG-2 (B), GFAP (C), and CD34 (D), and intermingled Neu-N-positive neurons (E)." (PMID 37409721, 2023).
tumor (continued). "Olig2 transcripts were detected in a subset of tumor cells, consistent with the heterogeneous expression shown by IHC." (PMID 37333134, 2023). "Reduced p-OLIG2 supports the on-target specificity of CT-179 in vivo and reduced p-RB shows that disrupting the OLIG2+ subpopulation produced a detectable anti-tumor effect." (PMID 37333134, 2023). "Considering that our FCCS studies of CT-179 confirmed the predicted mechanism of OLIG2 inhibition and that CT-179 showed low off-target effects and the favorable PK, we analyzed the anti-tumor potential of CT-179 in live cells in culture." (PMID 37333134, 2023). "In summary, this study shows that inhibition of OLIG2-positive MB tumor cells in combination with RT significantly slows MB progression in vivo." (PMID 37333134, 2023). "In this context, we demonstrated that indolent differentiated GBM cells feed aggressive tumor cell populations by spontaneously reprogramming into OLIG2-, NANOG-, and OCT4-positive cells with stem-like and tumorigenic properties." (PMID 37894405, 2023). "Tumor cells were diffusely positive for Synaptophysin, CD56, INI1, SMARCA4 and ATRX associated with negativity for GFAP, OLIG-2, EMA, BCOR, LIN28A, EZHIP, MIC-2, Cytokeratin’s, SMA, Desmin and Myogenin." (PMID 36934287, 2023). "CT-179 disrupted OLIG2 dimerization, DNA binding and phosphorylation and altered tumor cell cycle kinetics in vitro and in vivo, increasing differentiation and apoptosis." (PMID 37333134, 2023). "In summary, the diagnosis of EPN_PFA must include tumor location, growth pattern, Olig2 expression, and DNA-methylation profiling before it can be differentiated from DMG, H3 K27-altered." (PMID 36104744, 2022). "Overall, there was significantly decreased in Olig2 and Ki67 positivity in subependymal tumor in the intraventricular injection cohort, compared to intrapontine." (PMID 35733516, 2022). "OLIG2 + progenitor cells have recently been shown to represent a putative tumor-initiating cell population in mouse models of SHH MB and are also enriched in human SHH MB stem-like cells." (PMID 35835937, 2022). "A retrospectively performed staining against Olig2 showed a heterogeneous staining pattern, with large areas negative for Olig2 and smaller areas with a variable number of tumor cell nuclei stained." (PMID 35198980, 2022). "Two-way ANOVA revealed that in both treatment conditions, Olig2 intensity is higher near the tumor border, and that lucanthone resulted in reduction of Olig2 intensity at the tumor periphery and in the tumor core." (PMID 35494072, 2022). "Initial examination revealed that the density of Olig2+ cells was highest near the periphery of the tumor, though we did observe a significant number of Olig2+ cells near the core as well." (PMID 35494072, 2022). "Jin and colleagues observed in tumor tissue samples that GSCs with PN signal (Sox2+ and Olig2+) were located in perivascular niches, while GSCs with Mes signal (CD44+ and YKL40+) occupied exclusively hypoxic/necrotic regions." (PMID 35205179, 2022). "Tumor cells also expressed synaptophysin (Syn), oligodendrocyte transcription factor 2 (Olig2), and Ki-67 positivity less than 5%." (PMID 36531047, 2022). "An increased Euclidean distance to its nth neighbor would indicate that, on average, larger heterogeneity in morphology, Olig2 intensity, and Olig2 texture is present in tumor cell nuclei." (PMID 35014126, 2022). "These in vitro results were recapitulated in vivo: Tumors derived from control-treated mice exhibited robust Olig2 intensity, especially at the tumor border." (PMID 35494072, 2022).
tumor (continued). "Meanwhile, we found that both PHB KO and PHB inducible-KD resulted in a pronounced reduction of SOX2+ or Olig2+ tumor cells in GBM xenografts, suggesting a decrease of GSC pool in PHB-deleted tumors." (PMID 34140524, 2021). "In the early stages of tumor growth at P5, both G-Smo and M-Smo tumors consisted mostly of OLIG2+ stem cells." (PMID 34021242, 2021). "Other GSC markers: NES and OLIG2 are in much higher abundance and are present both in tumours and their margin." (PMID 34948016, 2021). "Further characterization of the CD109-silenced MES-like xenografts revealed a significant reduction in the number of Ki-67–positive proliferating tumor cells and OLIG2-positive GSCs." (PMID 33986188, 2021). "OLIG2 is upregulated in the proneural tumours, according to its role as a differentiation biomarker." (PMID 34123356, 2021). "The neoplasm was mainly composed of round, uninucleate cells with hyperchromatic nuclei, which were immunopositive for OLIG2, doublecortin, MAP2, synaptophysin, and vimentin, indicating components of both oligodendroglial and neuronal differentiation." (PMID 34977226, 2021). "snRNP70 was less abundant in the perilesional region than in tumor area (p=0.0046) although OLIG2 and PTN were expressed at similar levels in the corresponding samples." (PMID 35047379, 2021). "We also found that OLIG2+ cells frequency differed among sites: more cells with OLIG2 expression were in margin than in tumour." (PMID 34948016, 2021). "Olig2-expressing tumor stem cells, Ccr2+ macrophages, and Igf1+ microglial have all been shown to affect tumor progression and prognosis." (PMID 34021242, 2021). "Pairwise comparison of the margin and the tumour-adjacent to the margin shows a significant change in OLIG2+ cells frequency (p = 4.9 × 10−4)." (PMID 34948016, 2021). "To confirm the differential expression of Olig2 at the protein level and to compare the temporal course of Olig2 expression efficiently between genotypes, we labeled tumor sections using IHC." (PMID 34021242, 2021). "Our scRNA-seq data showed that both oligodendrocytes and tumor stem cells express Olig2, and that oligodendrocytes can be distinguished from stem cells by the expression of Sox10." (PMID 34021242, 2021). "Our results show that Imaging-AMARETTO recapitulates known key drivers of tumor-associated microglia and macrophage mechanisms (STAT3, AHR, and CCR2) and neurodevelopmental and stemness mechanisms (OLIG2)." (PMID 32383980, 2020). "To assess the functional significance of SUMOylation on the ability of Olig2 against tumor apoptosis, we measured apoptotic responses of the ETO-treated Neuro-2a cells." (PMID 32483381, 2020). "As expected, tumor core was enriched for CD109+ cells, while tumor edge contained more Olig2+ cells." (PMID 32938908, 2020). "The role of Olig2 in propagating tumor growth and the antiproliferative effect of Olig2 deletion was recently shown." (PMID 32160197, 2020). "Tumor cells show OLIG2 expression, indicative among others for gliomas, including pilocytic astrocytoma and high-grade astrocytoma or oligodendroglioma." (PMID 32103286, 2020). "The more in-depth understanding of the Olig2 SUMOylation regulated pathway described here at the molecular level will facilitate the design of new strategies for treatment of tumor resistant to genotoxic stress, such as GBM." (PMID 32483381, 2020). "Constant with the single cell sequencing and the immunohistological results from previous studies, we found the presence of Olig2+ tumor OPCs in human GBMs regardless the molecular subtypes or mutations." (PMID 33173731, 2020). "It was described that POU3F2, SOX2, SALL2, and OLIG2 maintain the tumor-forming capability of these cells." (PMID 32634135, 2020).